Y_RNA (Y RNA )
Gene: Miscellaneous RNA gene on chromosome 1 (206,747,980 to 206,748,092, reverse strand). Ensembl gene ENSG00000199349.
Homologues: Orthologues: chimpanzee Y_RNA (99% identical). Paralogues in human: RNY1 (86% identical), Y_RNA (85% identical), Y_RNA (84% identical), RNY1P11 (83% identical), Y_RNA (83% identical), Y_RNA (82% identical), Y_RNA (81% identical), Y_RNA (80% identical), RNY1P5 (79% identical), RNY1P8 (79% identical), Y_RNA (79% identical), RNY1P7 (78% identical), and 96 more.